BRCA1 (BRCA1 DNA repair associated)
Diseases named in the same sentence as BRCA1 in open-access papers (continued):
Sharing a sentence is not in itself a finding about the gene and the disease.
cancer (continued). "For the combined likelihood ratio (LR), we compared personal/family cancer history between the pathogenic (349 cases in BRCA1+, 291 cases in BRCA2+) and benign (2931 cases) groups." (PMID 34063308, 2021). "This literature review addresses cancer predisposition genes, including BRCA1, BRCA2, and PALB2; synthetic lethality in the context of DNA repair machinery; and historical and current treatment options for breast and ovarian malignancies with these mutations." (PMID 34070674, 2021). "PARP-1 inhibitors have not only been used in BRCA1/2 deficient cancers but also used in combination therapy with DNA-damaging therapeutics to improve their potencies by blocking DNA-repairing process." (PMID 35424391, 2021). "Synthetic lethality is a novel paradigm in cancer treatment regimens that combines a cancer-inherent genetic mutation (such as BRCA1 or BRCA2 mutation) with the pharmacological inhibition of a specific molecular target (such as PARP1)." (PMID 34572428, 2021). "By exploiting synthetic lethality, PARP inhibitors (PARPi) are used in clinic to treat various cancers defective in DNA repair via homologous recombination (HR), particularly those due to BRCA1/2 loss of functions." (PMID 33868586, 2021). "Topoisomerase 1 inhibitors have been shown to be effective in cancer therapy of HR-deficient, Schlafen 11-positive cells in association with Olaparib, for the treatment of BRCA1-, BRCA2-, and PALB2-deficient cells." (PMID 34639169, 2021). "In particular, the success of Olaparib and other PARP inhibitors in the treatment of TNBC with BRCA1/2 mutation brings hope to patients suffering from this refractory cancer." (PMID 34880209, 2021). "Patients with cancer mutations of BRCA1 and BRCA2 have shown remarkable sensitivity to recently developed poly(ADP-ribose) polymerase (PARP) inhibitors (PARPi)." (PMID 33391401, 2021). "Previous reports have demonstrated that women carrying a pathogenic mutation in the BRCA1 or BRCA2 genes have an increased risk of developing a second primary cancer in the contralateral breast." (PMID 34490083, 2021). "Prostate cancer (PCa) is the second most-common cancer in men, and various factors such as family history, advanced age, low testosterone levels, diet rich in fats and BRCA1/2 mutations are associated with the cancer progression." (PMID 34876936, 2021). "About 10–20% of breast/ovarian (BC/OC) cancer patients undergoing germline BRCA1/2 genetic testing have been shown to harbor Variants of Uncertain Significance (VUSs)." (PMID 34178674, 2021). "The unaffected cancer-free daughter aged 19 of the proband carried another mutation, BRCA1: c.4065_4068delTCAA; p.Asn1355Lysfs*10." (PMID 33477375, 2021). "This nationwide study assessed the impact of nationally agreed cancer genetics guidelines on use of BRCA1/2 germline testing, risk management advice given by health professionals to women with pathogenic BRCA1/2 variants and uptake of such advice by patients." (PMID 33836815, 2021). "Cancer surveillance in children affected by bi-allelic BRCA1/2 variants needs to recognise the association with embryonal tumours of childhood and include imaging for brain and other solid malignancies." (PMID 34680915, 2021). "By contrast, antioxidant treatment (4-hydroxy-2,2,6,6-tetrametylpeperidine-N-oxyl, tempol) suppressed the levels of estrogen-induced oxidative DNA lesions, and significantly delayed the onset of Brca1-deficiency-induced cancer development." (PMID 33498875, 2021). "In other cancers, signature 3 mutations often accompany biallelic inactivation of BRCA1 or BRCA2, where the inability to repair DNA predicts good responses to platinum therapy." (PMID 34580349, 2021).
cancer (continued). "Because of a family history of cancers, the patient was tested and found positive for a pathogenic BRCA1 germline and somatic mutation, which motivated bevacizumab plus olaparib maintenance treatment." (PMID 33888155, 2021). "The breast cancer susceptibility protein BRCA1 and its partner BRCA1-associated RING domain protein 1 (BARD1) form an E3-ubiquitin (Ub) ligase complex that acts as a tumor suppressor in mitotic cells." (PMID 33593852, 2021). "The prevalence and contribution of BRCA1/2 (BRCA) pathogenic variants (PVs) to the cancer burden in Latin America are not well understood." (PMID 34413315, 2021). "As there are definitive health risks for carriers and their family members, there is a need for better community education on the hereditary cancer risk of BRCA1/2, including for males." (PMID 33477375, 2021). "The application of synthetic lethality also depends on the RAD52 inhibition in cancer cells bearing BRCA1/2 mutations or the suppression of the BRCA1-RAD51 pathway." (PMID 34359720, 2021). "In agreement, we found a loss of α-SAT repeats in BRCA1-null cancer cells compared to that in wtBRCA1-complemented cells, indicating that BRCA1 is critical for centromeric repeats stability." (PMID 34599155, 2021). "This is because the incidence of BRCA1/2 germline mutations in these cancers is much lower than that in HBOC, making it difficult to perform large-scale clinical trials." (PMID 33563323, 2021). "Since 2009, when a first-in-human clinical trial of olaparib confirmed the synthetic lethal interaction between inhibition of PARP1, a key sensor of DNA damage, and BRCA1/2 deficiency, PARPi therapies have been approved for the use in several cancers." (PMID 33800556, 2021). "PARPi selectively induce synthetic lethality in cancer cells with homologous recombination deficiencies (HRDs), the most notable being cancer cells harboring mutations in the BRCA1 and BRCA2 genes." (PMID 33487630, 2021). "Amongst these, ‘breast cancer 1, early onset (BRCA1)’; ‘BRCA1 associated RING domain 1 (BARD1)’; ‘BRCA1 interacting protein C-terminal helicase 1 (BRIP1)’; ‘H2A histone family, member X (H2AFX)’ and RAD51." (PMID 33491125, 2021). "Since the discovery of synthetic lethality of PARPi with BRCA1/2-deficient cancer cell lines, there have been many studies to discover other synthetic lethality interactions related to DNA repair." (PMID 33784323, 2021). "Based on the clinical observations, carcinomas carrying mutations in hereditary tumor-suppressor genes involved in maintaining genome integrity such as BRCA1/2 have worse prognosis and aggressive behavior." (PMID 33540843, 2021). "Since the discovery of BRCA1 in 1994, 27 cancer predisposing genes that confer significant lifetime risk to hereditary adult cancers have been discovered." (PMID 32726901, 2020). "PTEN and BRCA1 are powerful tumor suppressors in cancer and loss of them will accelerate the process of tumor development." (PMID 32756009, 2020). "“USPSTF Calls for More BRCA Screening” is a recent US Preventive Services Task Force statement reiterating the importance of screening for BRCA1/2 mutations, especially for those with a personal history of certain cancer types and certain ancestries." (PMID 32349445, 2020). "Surgical resection of ovaries, fallopian tubes, and breasts is currently the most effective means of cancer risk reduction in individuals with germline BRCA1 mutations." (PMID 32120796, 2020). "First, the identification of a germline BRCA1/2 mutations impacted cancer screening and prevention practices in this subgroup of patients and their relatives." (PMID 32605126, 2020). "Individuals with a DDR-related cancer can include those with a pathogenic, germline or somatic BRCA1/2 variant and other genes within the homologous recombination and Fanconi anemia pathways." (PMID 32793315, 2020). "We have identified the intronic BRCA1 variant c.5407-25T>A in 20 families recruited from cancer genetics clinics." (PMID 32203205, 2020).
cancer (continued). "Accordingly, HR-deficient cancers (e.g., due to BRCA1/2 mutations) are often sensitive to classical DNA-crosslinking agents such as platinum-based drugs." (PMID 32432041, 2020). "BRCA1/2 mutation carriers are faced with complex decisions within breast (and ovary) cancer risk management." (PMID 31832891, 2020). "The relatively low immune activity in cancers (breast and ovarian) from BRCA1/2 germline mutation carriers is counterintuitive." (PMID 32164626, 2020). "Mutation-specific cancer risks and the existence of either BC and OC cluster regions have also been reported before for BRCA1/2." (PMID 32359370, 2020). "We found a significant association between germline BRCA1 PTVs and templated insertions at the pan-cancer level (P = 4 × 10−15)." (PMID 32025007, 2020). "PARP1 inhibitors are used for the treatment of BRCA1-deficient cancers, as inhibition of PARP1 generates more single-strand DNA damage, which results in DSBs and consequently leads to a synthetic lethality with BRCA1 deficiency." (PMID 32591500, 2020). "ID4 was amplified at twice the frequency in BRCA1-mutant BLBC (~ 22%, 21/97 cases) compared to sporadic BLBC (~ 10%, 4/42 cases), indicating a selection for ID4 amplification in cancers arising in patients carrying a mutant BRCA1 allele." (PMID 32527287, 2020). "RRSO was associated with an 85% reduction in BRCA1-associated gynecological (ovarian, fallopian tube, or primary peritoneal) cancer risk." (PMID 32098383, 2020). "Identification of individuals who carry pathogenic/likely pathogenic variants (PV/LPV) in BRCA1/2 genes has improved our ability to manage, support, and counsel individuals and their family members who are at an increased risk of cancer." (PMID 33110458, 2020). "Since cancer cells with BRCA1 mutations mostly rely on PARP1 to repair damaged DNA for survival, PARP inhibitors can sensitize the cancer cells inducing synthetic lethality." (PMID 33330383, 2020). "Further studies on an extended number of families with BRCA1 c.5407-25T>A are warranted to estimate the associated cancer risk, which would be most helpful for the clinical management of patients with this rare intronic variant." (PMID 32203205, 2020). "Prompt detection of BRCA1/2 PVs in women allows for surveillance and/or risk-reducing (RR) strategies, which have been demonstrated to reduce cancer-related morbidity and mortality." (PMID 32884827, 2020). "There is a need for algorithms which identify the BRCA1/2 gene mutation negativity in a short time and enabling the planning treatment rapidly by reducing the health costs and workload of cancer genetics polyclinic and laboratory." (PMID 33488844, 2020). "This was approved for the treatment ofovarian cancer, following a phase II trial in which 34% of patientsexhibiting BRCA1/2 mutations showed compelling response rates." (PMID 33135887, 2020). "Approximately 30% of these new diagnoses have a family history of these cancers, a quarter of which are due to a pathological gene mutation in either the breast cancer type 1 or type 2 susceptibility genes (BRCA1 and BRCA2, respectively)." (PMID 32513307, 2020). "In fact, it has been found that the breast cancer susceptibility 1 (BRCA1) gene interacts with and induces Nrf2 expression with positive outcomes on cancer cell survival." (PMID 32060354, 2020). "Loss of functional BRCA1 protein leads to defects in DNA double-strand break (DSB) repair by homologous recombination (HR) and renders cells hypersensitive to poly (ADP-ribose) polymerase (PARP) inhibitors used to treat BRCA1/2-deficient cancers." (PMID 32041954, 2020). "Multi-gene panels that usually contain known high-risk cancer predisposing genes, such as BRCA1 and BRCA2, were used to determine the prevalence and spectrum of variants in the genes in defined study groups for comparative purposes." (PMID 32726901, 2020). "The identification of the BRCA1/2 gene mutations is significantly important in the selection of treatment and the risk of secondary cancer." (PMID 33488844, 2020).
cancer (continued). "As one example, 42% of the intronic sequences of BRCA1 are made up of Alu repeats that range in size from 0.5 kb–23.8 kb, and erroneous recombination between them is one of the most frequent causes of mutation in BRCA1 deficient cancers." (PMID 32660124, 2020). "Normally, PARP1 is upregulated in breast, uterine, ovarian, lung, and skin cancers but is highly expressed in certain cancer types with BRCA1 mutations that display defects in homologous recombination (HR)." (PMID 33330383, 2020). "Olaparib’s mechanism of action follows a concept of synthetic lethality: this drug selectively targets cancer cells with hereditary BRCA1/2 mutations." (PMID 33114555, 2020). "This means that among women with a BRCA1 mutation in Poland, the risk of cancer at age 40 is much higher than that in the general population, but the odds ratio cannot be generalized to older women." (PMID 32824581, 2020). "Mutation in BRCA1 or BRCA2 in HR-deficient cancer cells will lead to the repair of DSBs via error-prone repair pathways, accumulation of mutations and eventually cell death." (PMID 32316968, 2020). "Recent advances in the detection of germline pathogenic variants (PVs) in BRCA1/2 genes have allowed a deeper understanding of the BRCA-related cancer risk." (PMID 32380732, 2020). "Together with improved availability of genetic testing, this has led to lower testing thresholds and more germline diagnostic tests, resulting in an increase of cancer patients with known germline pathogenic variants in BRCA1/2." (PMID 32655641, 2020). "Large cohorts of breast cancer show that ~ 2% of cancer cases are associated with mutations in BRCA1 and BRCA2 which are also high-risk ovarian cancer susceptibility genes." (PMID 32778766, 2020). "In the present study, we analyzed the association of BRCA-related cancer risk and metabolic factors with BRCA1/2 variant type and position in a cohort of 438 female carriers who joined our dietary randomized controlled trial." (PMID 33266155, 2020). "DNA of patients with a family history of cancer was extracted from saliva and screened for pathogenic variants in the BRCA1/2 genes as the first step using WES." (PMID 32231682, 2020). "PARP inhibitors are Food and Drug Administration (FDA)-approved drugs that target cancers with defects in HR, including those with BRCA1 or BRCA2 mutations." (PMID 32570740, 2020). "Using the Sleeping Beauty transposon system in Brca1-deficient mice, we identified 169 putative cancer drivers, among which Notch1 is a top candidate for accelerating TNBC by promoting the epithelial-mesenchymal transition (EMT) and regulating the cell cycle." (PMID 32591500, 2020). "This work is ongoing anddemonstrates one of the first programs targeting small molecule-inducedsynthetic lethality and a way to expand the use of PARPi’sbeyond BRCA1/2 deficient cancers, increasing their usefulness." (PMID 33135887, 2020). "Because of their high risk of developing cancer, unaffected women carrying BRCA1/2 germline pathogenic variants perfectly represent this category of patients and illustrate the practical and ethical issues that their risk status entails." (PMID 33031463, 2020). "In this work, we retrospectively collected and analyzed all clinical information of 139 BBC patients who have been genetically tested for germline PVs in different cancer susceptibility genes, including BRCA1 and BRCA2, by NGS-based multi-gene panel testing." (PMID 32854451, 2020).
cancer (continued). "Due to the importance of PARP1 for the bulk of PARylation upon DNA damage, RNAi-mediated depletion or single RNA-mediated mutation of PARP1 induces synthetical lethality in BRCA1/2-deficient cancer cells." (PMID 33324554, 2020). "Identification of one’s status as a BRCA1/2 pathogenic variant carrier often marks the start of navigating challenging decisions related to cancer risk management and result disclosure." (PMID 33110458, 2020). "These predictions critically depend on external cancer incidence estimates for BRCA1/2 pathogenic variant carriers, which themselves are uncertain and therefore should only be used as a general guide." (PMID 32665703, 2020). "Despite the lack of malignant enhancement by MRI, the evolution of the discharge character from serous to bloody, and an underlying BRCA1 mutation, elevated our concern for a missed diagnosis of cancer." (PMID 32967733, 2020). "One such molecular driver of a subset of BLBCs is mutation in the breast and ovarian cancer susceptibility gene (BRCA1)." (PMID 32527287, 2020). "Approximately 16% of women with a BRCA1 or BRCA2 mutation experience distress levels comparable to those of women after a cancer diagnosis." (PMID 32393849, 2020). "This was correlated clinically in a cohort of HGSOC specimens in which BRCA1-deficient cancers with low expression of DYNLL1 were associated with fewer chromosomal abnormalities." (PMID 32722408, 2020). "Intervention with PARP-1 has been proved to be more sensitive to cancer cells carrying BRCA1/2 mutations." (PMID 32779949, 2020). "Olaparib inhibits BRCA1/2 mutated cancer cells that have an increased reliance on PARP to repair their damaged DNA and therefore are more vulnerable to olaparib treatment." (PMID 32947941, 2020). "Phosphorylation of RPS6 is greatly increased in BRCA1-deficient cancer cells, which are resistant to PARP inhibition." (PMID 32640701, 2020). "The number of recalls and biopsies needed to detect one cancer by biannual MRI were 2.8 and 1.7, respectively, in BRCA1 mutation carriers and 12.0 and 8.0, respectively, in BRCA2 mutation carriers." (PMID 33238387, 2020). "The recent discovery of PARP inhibitors leads to researches regarding genetic associations between potential therapeutic targets and cancer genes for BRCA1/2-mutated cancer patients." (PMID 32883316, 2020). "The impact of RAD52 inhibition on tumor suppression needs to be further validated before inhibitors can be tested for cancer prevention in BRCA1/2 mutation carriers." (PMID 32255263, 2020). "Studies on the cancer risk of fertility treatment in women with mutations in the genes BRCA1 and BRCA2 are sparse." (PMID 32719921, 2020). "Collectively, our results establish a new paradigm for the PRIMPOL protein in replication fork protection and revisit current models for how BRCA1-deficient cancer cells cope with cisplatin-induced lesions." (PMID 31676232, 2020). "For deleterious SAVs, the lowest correlation was that between two measurements on breast cancer type 1 susceptibility protein, BRCA1 and BRCA1_2015_E3 (ρ = 0.21)." (PMID 32183714, 2020). "This further suggests that the aberrant DNA methylation pattern underlies the deregulation of BRCA1 gene expression in human cancer." (PMID 31963223, 2020). "In our cohort 46 patients (34 BC, 10 OC and 2 BC + OV) didn’t harbor any BRCA1/2 pathogenic variant or copy number variation, despite having a strong family history for cancer." (PMID 32778078, 2020). "We argue that the primary function of 53BP1 is not to regulate the choice between c-NHEJ and HDR, but to ensure the fidelity of DSB repair, a function that is corrupted in diseases where DNA repair is rewired, as in BRCA1-deficient cancers." (PMID 31896689, 2020). "Women carrying pathogenic BRCA1 or BRCA2 variants have different opportunities to manage their cancer risk." (PMID 33031463, 2020).